IL1B (interleukin 1 beta)
Diseases named in the same sentence as IL1B in open-access papers (continued):
Sharing a sentence is not in itself a finding about the gene and the disease.
Obesity (continued). "While the translation of animal studies to humans is difficult, the discrepancy in observed expression levels of IL1B in obesity associated NASH and pericellular fibrosis maybe attributed to the extremely high BMI of the cohort being examined (BMI ≥ 35)." (PMID 25512222, 2014). "Blocking IL-1β could be beneficial for preventing obesity-associated insulin resistance and inflammation in human adipose tissue." (PMID 24918199, 2014). "Both are related with obesity while IL-1β is also linked with obesity-induced diabetes." (PMID 24302970, 2013). "A decline in IL10 concentration in overweight and obese adolescents may further contribute to the IL1β-mediated inflammatory environment associated with obesity." (PMID 23941335, 2013). "Although the overall conclusion (i.e., of a key role for the IL-1β/IL-1R in obesity-associated adipose tissue inflammation) is well consistent with the findings in IL-1RIKO mice, the inconsistencies are also worth noting given that both models target the exact biological system." (PMID 23341960, 2013). "Our results suggest that IL-1β blockade could have important effects on the endocrine function of adipocytes and consequently on the development of obesity-associated comorbidities." (PMID 23460908, 2013). "A decline in serum IL10 concentration in overweight and obese adolescents may further contribute to the IL1β-mediated inflammatory environment associated with obesity." (PMID 23941335, 2013). "Moreover, we show that 1,25(OH)2D3 also inhibits adipocyte production of the major cytokines IL-1β and IL-6, both of which are critically involved in obesity associated inflammation and insulin resistance." (PMID 23637889, 2013). "Furthermore, these knock out models display reduced macrophage infiltration into insulin sensitive organs along with reduced cytokine secretion from BMM indicating a potential role for IL-1β in maternal UN-mediated obesity and associated co-morbidities." (PMID 23844177, 2013). "The IL-1B C-31T polymorphism is associated with obesity in Japanese." (PMID 19398847, 2009). "The association between IL-1B C-31T genotypes and various indices of obesity was then investigated." (PMID 19398847, 2009). "We suggest that this mechanism is one reason for the effect of IL-1B C-31T polymorphism on obesity." (PMID 19398847, 2009). "We therefore investigated the association between IL-1B C-31T polymorphism and obesity in Japanese." (PMID 19398847, 2009). "Furthermore, the low-grade systemic inflammation caused by some molecules such as interleukin-6 (IL-6), IL-1β, TNFα, leptin, and adiponectin may play a role in obesity association with KOA." (PMID 39472918, 2024). "Furthermore, the low-grade systemic inflammation associated with obesity not only increases periodontal inflammation but promotes bone resorption processes caused by the recruitment of immuno-inflammatory cells and certain cytokines (IL-1β, TNF)." (PMID 37894804, 2023). "However, the regulation of inflammatory genes seemed to be restricted to a small number of genes (for example, CX3CR1 and IL1B), as most genes associated with inflammation remained unchanged, indicating an overall subtle inflammatory response during obesity in humans." (PMID 37414931, 2023). "Interestingly, the finding that in renal cell carcinoma, obesity is associated with a diminished efficacy of PD-1 blockade, has been ascribed, at least in part, to the presence of constitutively elevated IL-1β levels which can also frequently found in the microenvironment of cHL." (PMID 34852840, 2021). "Since elevated levels of IL-1β and TNFα have been previously linked to obesity-induced inflammation and the development of insulin resistance in adipose tissue adipokines, we investigated whether these two agents interact to trigger IL-6 production in adipocytes." (PMID 34831450, 2021).
Obesity (continued). "Finally, a positive association was found between the Deferribacteres and Il-1β expression, suggesting that the increase in Deferribacteres observed in obesity could contribute to the overexpression of inflammatory cytokines in the colonic mucosa." (PMID 32751593, 2020). "Furthermore, activation of the Nlrp3 inflammasome in Wt C57BL/6 or Nlrp1b1-Tg bone marrow derived macrophages in response to ATP or danger signals associated with obesity like glucose or palmitic acid resulted in similar levels of IL-1β secreted to the culture supernatant." (PMID 31554824, 2019). "Obesity as a low-grade chronic inflammation has been associated with tissue hypoxia/necrosis with consecutively upregulation of the pro-inflammatory response via cellular (M1/2 macrophage—Th1/Th2 cells phenotype transformation) and molecular (IL-1β, IL-6, TNF-α) pathways." (PMID 30795781, 2019). "Moreover, direct participation of NLRP3 in obesity has been confirmed in studies that have shown that in gene-deficient mice fed with a high-fat diet, activation of caspase-1 and expression of pro-IL-1b in adipose tissue, and serum loss of IL-18 compared to the wild-type phenotype is reduced." (PMID 28319103, 2017). "Obesity has been discovered to be associated with excess adipocyte hypertrophy generating a proinflammatory state through secretion of inflammatory cytokines and chemokines, including interleukin (IL)-1β, IL-6, IL-8, monocyte chemoattractant factor, tumor necrosis factor-α, and C-reactive protein." (PMID 26658675, 2015). "Obesity-associated inflammation occurs as a result of immune cell infiltration into the adipose tissue and increased production of pro-inflammatory cytokines such as IL–1β, IL–6 and TNF-α, leading to the pathogenesis of insulin resistance and eventually to the development of type 2 diabetes." (PMID 26437377, 2015). "Furthermore, IL1B polymorphisms may interact with obesity, as the effect of obesity on plaque development is partly mediated by the release of inflammatory cytokines from adipose tissue compartments." (PMID 22768033, 2012). "Likewise, we hypothesized that the combined effect of SNP haplotypes associated with higher levels of IL-1B expression and obesity would be additive or greater." (PMID 22768033, 2012). "Importantly, obesity is associated with chronic low-grade inflammation, and a high-fat diet increases the proinflammatory cytokines IL1-β, tumor necrosis factor alpha (TNF-α), C-reactive protein (CRP), and IL1-6 and stimulates inflammatory signaling in adipose, serum, liver, and brain." (PMID 22144990, 2011). "However, the association between interleukin-1beta (IL-1β) and obesity remains controversial." (PMID 19398847, 2009). "Elevated levels of pro-inflammatory cytokines such as TNF-α, IL-1β, and IL-6 are observed in ovarian conditions including obesity, polycystic ovary syndrome, endometriosis, and reproductive aging." (PMID 41625246, 2026). "The adipose tissue in obesity secreted pro-inflammatory cytokines, such as IL-1β and IL-6, while simultaneously impairing the secretion of anti-inflammatory adipokines like adiponectin." (PMID 41009007, 2025). "The induction of obesity (group 2) led to a significant increase in all monitored inflammatory interleukins compared to the control group (group 1), as observed for IL-1β, IL-6, IL-8, TNF-α, and C-reactive protein, with p < 0.0001 in all cases." (PMID 40565191, 2025). "Adipose tissue also produces a variety of adipokines and proinflammatory cytokines linked to obesity-associated male infertility, including leptin, adiponectin, resistin, ghrelin, TNF-alpha, IL-1β and IL-6." (PMID 40140188, 2025). "The NPC degeneration model was established using PA and IL‐1β to mimic inflammation‐related IVDD under obesity conditions." (PMID 40090836, 2025). "Monocytes from individuals living with obesity exhibited an increased viral load and elevated gene expression of IL‐6 and pro‐IL‐1β compared to those from lean/overweight individuals." (PMID 40265287, 2025).
Obesity (continued). "Elevated IL-1β and IL-18 levels are consistently observed in the adipose tissue and serum of individuals with obesity and insulin resistance, and higher NLRP3 expression in visceral adipose tissue correlates with the severity of insulin resistance." (PMID 40943225, 2025). "We herein aimed to study how obesity and CC affects the expression of IL1B, and to determine the impact of IL-1β on the regulation of metabolic inflammation and gut barrier function in the context of obesity and CC." (PMID 39305371, 2025). "We found that blood samples of individuals living with obesity or palmitate priming enhanced the acetylation of H3K18 and is associated with increased gene expression of this IL‐6 and pro‐IL‐1β." (PMID 40265287, 2025). "The pro-inflammatory cytokines IL-1β and IL-36γ, often elevated in obesity, activate procarcinogenic signaling pathways such as the Wnt signaling cascade, leading to increased epithelial proliferation and tumorigenesis in the colon." (PMID 40722646, 2025). "Previous studies established that obesity-associated adipose inflammation is primarily driven by macrophage polarization (M1-type) and TNF-α/IL-1β overexpression, with CD8+ T-cell infiltration as an early trigger." (PMID 40725440, 2025). "For instance, in humans, obesity is associated with chronic low-grade systemic inflammation, often marked by elevated cytokines like TNF-α, IL-6, and IL-1β." (PMID 40266905, 2025). "For example, pro‐inflammatory pathways (NF‐κB, JNK) and cytokine signaling (e.g., CRP, IL‐1β) drive IR and β‐cell stress, while PPARγ and leptin signaling mediate obesity‐driven IR." (PMID 40673471, 2025). "The activation of the inflammasome and its target cytokines, IL-1β and IL-18, are important mediators in innate immunity and contribute to the development of obesity-induced inflammation and insulin resistance." (PMID 41301516, 2025). "Cytokines like TNF-α, IL-1β, and IL-6 not only fuel tumor growth in obesity-afflicted mouse models but also parallelly increase in obese women, closely correlating with the onset and progression of breast tumors." (PMID 40040878, 2025). "Chronic inflammation is linked to obesity, generating proinflammatory cytokines such as TNF-α, IL-6, IL-1β, and IL-18 that activate NF-kB." (PMID 40703753, 2025). "In obesity, hypertrophic adipocytes release a spectrum of pro-inflammatory adipokines (e.g., leptin and resistin) and cytokines (e.g., IL-1β and IL-6), which are known to exacerbate autoimmune conditions." (PMID 40900762, 2025). "GSDF induces a decrease in the expression of inflammatory proteins like IL-1β and TNF-α in tissues through its regulatory action, inhibits the occurrence of tissue inflammation, and improves the damage to eWAT caused by obesity." (PMID 40428495, 2025). "In our cohort, individuals with obesity showed elevated plasma Ang II, heightened concentrations of IL-1β, IL-6, and TNF, and reduced IL-10, supporting the presence of a dysregulated inflammatory state exacerbated by viral infection." (PMID 41562075, 2025). "IL-1β, a key pro-inflammatory cytokine typically found at elevated levels in obesity, plays a critical role in bone remodeling by enhancing osteoclastogenesis." (PMID 40565082, 2025). "The common mechanisms that bromelain can interfere with are the reduction in pro-inflammatory cytokines (TNF-α, IL-1β, IL-6), which are excessively produced both in obesity (by macrophages in adipose tissue) and in other inflammatory conditions." (PMID 40943267, 2025). "The literature has already demonstrated the elevated mRNA expression of caspase-1 and IL-1β in patients with obesity and diabetes compared to eutrophic patients." (PMID 40004007, 2025). "In rats with obesity induced by monosodium glutamate, an elevation of proinflammatory cytokines IL-1β and IL-12B p40 was registered, coupled with downregulation of the anti-inflammatory system, as evidenced by reduced IL-4, IL-10, and TGF-β levels." (PMID 40259921, 2025).
Obesity (continued). "In the current study, obesity-induced inflammatory response was effectively ameliorated by exercise and YH administration by decreasing IL-1β and TNF-α levels." (PMID 40181294, 2025). "A significantly different behavior was shown between IG and CG in the overweight/pre-obesity subgroup for IL-1β (p = 0.014; Z = 2.430; r = 0.63) and TNF-α (p = 0.029; Z = 2.199; r = 0.57)." (PMID 40430061, 2025). "In individuals with obesity, pro-inflammatory cytokines such as interleukin-6 (IL-6), IL-1β, and tumor necrosis factor-α (TNF-α) can upregulate hepcidin, a central regulator of iron homeostasis." (PMID 41141252, 2025). "To further study how obesity affects the expression of IL1B in a CC context, we treated the colon adenocarcinoma HT-29 cell line with increasing concentrations of ACM obtained from patients with OB." (PMID 39305371, 2025). "We showed that obesity (P < 0.05) and CC (P < 0.01) upregulated the transcript levels of IL1B in visceral adipose tissue as well as in the colon from patients with CC (P < 0.01)." (PMID 39305371, 2025). "Given that obesity is a long-term inflammation potentially harming the liver, the presence of IL-1β, IL-6, and TNF-α in liver inflammation was identified using the ELISA kit." (PMID 39910919, 2025). "NLRP3, IL‐1β, and ILC3 cells also seem to play a role in obesity‐associated asthma and contribute to airway hyperresponsiveness associated with obesity‐associated asthma." (PMID 39800672, 2025). "We also discuss the potential role of IL-1β in obesity, Alzheimer’s disease, fatigue, gonadal dysfunction and related disorders such as rheumatoid arthritis and gout." (PMID 39496966, 2025). "Obesity is well known to drive low-grade chronic inflammation and can independently elevate IL-1β production." (PMID 41137275, 2025). "Inflammatory cytokines such as TNF-α, IL-1β, and IL-6 can reduce insulin sensitivity and promote obesity." (PMID 40298814, 2025). "Adipose tissue in individuals with obesity secretes pro-inflammatory adipokines and cytokines, such as leptin, IL-1β, and IL-6." (PMID 40218960, 2025). "IL-1β has been proposed as a key mediator in the crosstalk between macrophages and adipocytes during obesity." (PMID 40646891, 2025). "A statistically significant correlation between salivary IL-1β and obesity was found in Spanish children." (PMID 40565251, 2025). "In obesity, a persistent state of chronic inflammation is established, resulting in the secretion of pro-inflammatory cytokines such as IL-6, IL-1β, and TNF-α." (PMID 40565082, 2025). "Inflammation is also present in cases of obesity in childhood and adolescence, especially caused by cytokines such as MCP-1, IL-6, TNF-α and IL-1β." (PMID 40002337, 2025). "In this line, obesity reportedly induces the differentiation of pro-inflammatory macrophages, which in turn increases the production of IL-1β." (PMID 39305371, 2025). "Increased activity of the NACHT, LRR and PYD domains-containing protein 3 (NLRP3) inflammasome–IL-1β pathway is observed in obesity and contributes to the development of type 2 diabetes and its complications." (PMID 39496966, 2025). "We found that the levels of TNF-α in experimental obesity-related SAP were higher than IL-1β, IL-6, and IFN-γ, indicating its potential unique role." (PMID 39856555, 2025). "IL-1β levels, determined by ELISA, were markedly higher in the obese group, confirming our recent report that obesity promotes atrial NLRP3 inflammasome activation." (PMID 39283528, 2025). "In this context, specific pro-inflammatory cytokines such as TNF-α, IL-1β, and IL-6 have emerged as key players in the pathophysiology of obesity and its complications." (PMID 41141350, 2025). "Chronic low-grade inflammation, which is in part characterized by the excessive production of pro-inflammatory cytokines, such as TNF-α, IL-1β, IL-12, and IL-6 from expanded WAT, is a key driver of the metabolic dysfunction associated with obesity." (PMID 39684547, 2024).
Obesity (continued). "Nevertheless, administration with FLT, FBT, or orlistat for eight weeks significantly suppressed the liver’s TNF-α, IL-1β, and IL-6 expression levels (p < 0.05), thus alleviating the inflammation induced by obesity." (PMID 38254507, 2024). "A clear connection exists between cholesterol levels and pro-inflammatory cytokines, such as IL-1β and IL-6, particularly among participants dealing with overweight and obesity." (PMID 38178093, 2024). "SWELL1 and key markers of inflammation (NLRP3, NLRP6, IL1B, IL18 and IL8) were also upregulated in VAT in obesity and T2D being significantly associated (P < 0.01) with PIEZO1 levels." (PMID 39707172, 2024). "In the present study, we found a significant difference in the inflammatory markers TNF-α and IL-1β as compared to lean group with OW and OB groups; cats with OW and obesity had higher concentrations of these inflammatory markers." (PMID 39328456, 2024). "In obesity-induced type 2 diabetes, pro-inflammatory molecules like IL-1β, IL-6, CCL2, CCL5, and leptin play key roles in the accumulation of MDSCs in adipose tissue." (PMID 39518420, 2024). "A positive correlation of IL-1β has been observed with the accumulation of visceral fat in women with obesity grade I. Labrecque et." (PMID 39727499, 2024). "Obesity is recognized as a factor that can worsen AR symptoms, and simultaneously, it correlates with heightened levels of IL-1β and leptin." (PMID 38790590, 2024). "IL-1α and IL-1β exacerbate IR in obesity by impairing adipocyte function and promoting inflammation." (PMID 38622732, 2024). "Cytokines secreted by adipose tissue, such as IL-1β, IL-10, and IL-18, are elevated in both obesity and AD." (PMID 39273520, 2024). "Other myeloid immune cells, namely neutrophils, have been shown to transiently infiltrate the adipose tissue as early as 3 days following initiation of HFD and are identified as key drivers of obesity-induced increases in IL-1β." (PMID 38685031, 2024). "People with obesity experience chronic inflammation due to the endocrine function of adipocytes, which leads to a release of such pro-inflammatory cytokines as IL-6, IL-1β, and TNF-α." (PMID 39456224, 2024). "In chronic renal failure related to obesity, TNF-α, IL-1β, and IL-6 genetic overexpression was associated with chronic inflammation in adipose tissue." (PMID 39274918, 2024). "Activation of NLRP3 inflammasome-related gene expression with IL-1β exaggerates the asthmatic episode in patients with obesity and asthma." (PMID 39065704, 2024). "Because of IL-1β’s role in insulin resistance and obesity-induced inflammation, it has become the target of several clinical trials." (PMID 39606781, 2024). "It has been reported that the proinflammatory factors TNFα and IL-1β are increased and are involved in β-cell dysfunction in obesity and diabetes." (PMID 38693121, 2024). "Targeted knockout of NLRP3 at the level of the VAT attenuates diet-induced obesity cognitive deficits, thus implicating a potential role for NLRP3/IL-1β signaling in brain-visceral adipose tissue interactions related to obesity." (PMID 38685031, 2024). "Mitochondrial dysfunction is a key mechanism involved in the relationship between obesity and metabolic complications, leading to insulin resistance by inducing interleukin 1β (IL-1β) secretion through the activation of NRP3 inflammasome." (PMID 39518420, 2024). "Some studies also found that elevated levels of pro-inflammatory cytokines, such as IL-1β, IL-6, and TNF-α, associated with obesity can impair sleep architecture and promote sleep disturbances." (PMID 39267856, 2024). "Leptin resistance and inflammation demonstrated by higher plasma and central nervous system levels of interleukin-6 (IL-6), IL-1β and tumour necrosis factor-α, are mechanisms connecting obesity and diabetes with AD." (PMID 38290839, 2024).